OSM (oncostatin M)
Diseases named in the same sentence as OSM in open-access papers (continued):
Sharing a sentence is not in itself a finding about the gene and the disease.
tumor (continued). "Moreover, OSM expression was found to be enriched in Sox2 or Snail-high tumours from an in-house cohort of human invasive breast carcinoma, and positively correlated with the mesenchymal protein S100A7." (PMID 34361105, 2021). "Additionally, OSM-KO mice bearing 4T1.2-shLacZ tumors had 10-fold fewer CTCs and 2.5-fold fewer lung metastases than wild-type mice with the same tumor type (right)." (PMID 29898744, 2018). "However, the role of oncostatin M on cancer cell proliferation remains controversial as it has been proposed as both a tumor suppressor and a tumor promotor." (PMID 28481292, 2017). "In addition, we found that TDP2 high-expressing epithelial cells 2 may exert their effects through COLLAGEN, GALECTIN, MK, and OSM signaling pathways in tumor progression." (PMID 41481587, 2026). "However, emerging evidence indicates the role of OSM in neoplasia may be tissue dependent, and have a dynamic function, changing its role based on the stage of carcinogenesis." (PMID 39123444, 2024). "A previous study showed that the chemokines from monocyte and the signals from tumor microenvironment contributed to the production of the pro‐metastatic factor oncostatin M by neutrophils, which may be potential targets of immune‐based anticancer treatment for HCC patients." (PMID 36062301, 2022). "Interestingly, OSM was selectively overexpressed in hepatic cancer cells and progressively increased with the tumor grade, with serum OSM levels being enhanced as well and correlated with a poor outcome, suggesting OSM as a putative prognostic factor for NASH-associated HCC." (PMID 36077744, 2022). "Similarly, OSM was highly expressed in tumor cell lines of blood, lung and spleen." (PMID 34702277, 2021). "Interestingly, although the expression of OSM is positively correlated with the abundant immune cell infiltration inside the tumor, prognostic analysis proves that OSM usually leads to poor clinical outcomes, indicating the potential immune cell dysfunction in anti-tumor response." (PMID 34702277, 2021). "Therefore, OSM knockout mouse may serve as an ideal animal model to explore the effects of OSM on tumor development." (PMID 34702277, 2021). "In contrast to IFN-β, exposure of Ep/non-CSC to certain tumor-associated cytokines (such as OSM or TGF-β) can reprogram the cells to a CSC state (with the expression of CSC genes and associated biological activities, including tumor-initiating capacity, invasiveness, and resistance to chemotherapy)." (PMID 31036052, 2019). "Thus we propose that inhibiting Eotaxin and Oncostatin M functions using specific antibodies may represent an innovative approach to control macrophage homing and their M2 polarization and resultant tumor progression." (PMID 25051364, 2014). "In contrast, MG3, MG4, and monocyte subsets 1 and 2—which were less concentrated within tumor cores—exhibited significantly weaker engagement with pro-tumor or immunosuppressive pathways, including MIF, TNF, IL-4, IL-6, OSM, galectin, and TGF-β." (PMID 41503214, 2026). "In GBM, OSMR cooperates with its ligand OSM to activate STAT3 signaling, inducing a mesenchymal‐like phenotype that enhances tumor invasiveness and treatment resistance." (PMID 41498024, 2025). "Tumor secretion of GM-CSF, which increases neutrophil production and triggers Oncostatin M (OSM), a cytokine that increases VEGFα expression via the Jak/STAT pathway, is a crucial interaction between TANs and tumor cells that promotes angiogenesis." (PMID 41283276, 2025). "N2 TANs further promote metastasis by secreting oncostatin M (OSM) and HGF, which induce EMT in tumor cells." (PMID 41438763, 2025). "Taken together, these findings suggested that irisin, OSM, and GEN can impede tumor progression and shift towards M2 macrophages by suppressing the JAK1/STAT6 pathway." (PMID 40604704, 2025).
tumor (continued). "Oncostatin M (OSM), an IL-6 family cytokine primarily secreted by immune cells, has been shown to activate the STAT3 pathway in tumor cells via the OSM receptor (OSMR), thereby promoting tumor proliferation and metastasis." (PMID 41383622, 2025). "Further, curcumin downregulated the gene expression of factors secreted by tumor cells known to induce immunosuppression (VEGFA, PDGF, IL4, OSM, CXCR4 and Fas ligand)." (PMID 39861845, 2024). "Additional groups were treated with Anti-OSM antibody (SED + Anti-OSM and EX + Anti-OSM) to explore the impact of OSM blockade on tumor latency." (PMID 39123444, 2024). "In line with our findings, IL1 and OSM have been implicated in cancer-associated inflammation and therapy resistance and research has shown that blocking IL1 and IL6 family of inflammatory cytokines could enhance anti-tumor activity in head and neck squamous cell carcinomas." (PMID 39289380, 2024). "OSM-OSMR signaling pathway is crucial in the reprogramming of CAFs, thereby significantly impacting tumor metastasis, particularly in PDAC." (PMID 39286635, 2024). "We found that GDF, IGF, OSM, TNF, and TWEAK outgoing signaling pathways were all enriched from SCAMs towards the tumor epithelium." (PMID 37164949, 2023). "There have been studies identifying different, novel myokines which exhibit anti-tumour properties, such as the secreted protein acidic and rich in cysteine (SPARC) myokine, oncostatin M (OSM) and irisin." (PMID 38149260, 2023). "It is described that the prolonged neutrophil lifespan facilitates the secretion of pro-metastatic factors, such as oncostatin M and MMP-9, which promote the migration of tumor cells." (PMID 38136358, 2023). "Our results showed that pro-inflammatory and tumor-promoting factors MMP9, IL-8, OSM, IL-1β, TNF-α, CXCL3, and ROS all increased to varying degrees after OCOs stimulation." (PMID 37644468, 2023). "Myokines such as oncostatin M (OSM), secreted protein acidic rich in cysteine (SPARC), irisin, and decorin can directly restrain tumor development by blocking cell proliferation and migration and promoting tumor cell apoptosis." (PMID 37958310, 2023). "OSM was found to be selectively overexpressed in HCC cells of NAFLD/NASH patients, depending on tumor grade." (PMID 35064579, 2022). "Accordingly, OSM was upregulated in liver specimens of cirrhotic patients, carrying or not HCC, with the highest OSM levels correlating with advanced tumor stages." (PMID 36077744, 2022). "Here, we describe how heterocellular Oncostatin M (OSM) - Oncostatin M Receptor (OSMR) signalling reprograms fibroblasts, regulates tumour growth and metastasis." (PMID 34921158, 2021). "Neutrophils are a major source of oncostatin M (OSM) and vascular endothelial growth factor (VEGF), and facilitate metastasis by promoting the adhesion and migration of tumor cells on liver sinusoidal cells." (PMID 33573309, 2021). "Myokines, such as IL-6, irisin/FNDC5, decorin, oncostatin M (OSM), and secreted protein acidic and rich in cysteine (SPARC), have shown the potential of a direct tumor-suppressive effect in different cancer cell lines, including PCa." (PMID 34595123, 2021). "Since previous studies and our present result confirmed an important role of OSM in GBM, we have focused on this particular tumor type, exploring intercellular communication based on scRNA-seq data." (PMID 34702277, 2021). "IL-6 and OSM are clear EMP promoters and their role in tumour progression and metastasis is widely accepted." (PMID 34361105, 2021). "Analysis of normal tissue samples (GTEx) and human PDA tumours (TCGA PanCancer PAAD) revealed a significantly higher expression level of OSMR and its cognate ligand, OSM, in human PDA compared to normal pancreatic tissue." (PMID 34921158, 2021).
tumor (continued). "The neutrophils secrete several inflammatory, immunoregulatory and angiogenic factors, including NE, PR3, CathG, MMPs, VEGF, Bv8 (prokineticin 2), oncostatin M, IL-1β, TGFβ2, BMP2 and HGF, that modulate the tumor microenvironment and affect tumor growth." (PMID 34572138, 2021). "OSM is a cytokine member of the leukemia inhibitory factor/oncostatin-M (LIF/OSM) family and a growth regulator with important roles in inflammation and tumor growth inhibition." (PMID 32286411, 2020). "MDSCs also produce cytokines such as hepatocyte growth factor (HGF) and oncostatin M (OSM), which are pro-metastatic via induction of an invasive phenotype and detachment of tumor cells, respectively." (PMID 32244751, 2020). "OSM–OSMR signaling is a significant mediator of inflammatory disease, cell development, and is also considered an important mechanism in tumor progression." (PMID 30755233, 2019). "Restoring IFN-β signaling to OSM-driven CSC re-engages IFN-β-mediated differentiation by repressing OSM/STAT3/SMAD3-mediated SNAIL expression, tumor initiation, and growth." (PMID 31036052, 2019). "After five weeks of development, the tumor volume was the same for both OSMR-KO mice and their WT littermates, suggesting a direct role of OSM on OSMR-expressing cancer cells to promote tumor development." (PMID 30559930, 2018). "Neutrophils can also release oncostatin M and matrix metalloproteinase (MMP-9) to induce production of vascular endothelial growth factor, which can promote angiogenesis and invasion of tumor cells in multiple cancer models." (PMID 30473691, 2018). "Interleukin 6 (IL6)-type cytokines such as oncostatin M (OSM) are key players in the regulation of the immune response, the immune surveillance of tumor cells, and in the development of cancer." (PMID 26889381, 2016). "The cytokine Oncostatin-M, which is up-regulated after VACV infection, belongs to the IL-6 family and has cytostatic activities on a number of tumor cell lines." (PMID 25030093, 2014). "Priming by tumor cells upregulated EREG, TGFA and OSM transcripts in PBMC within 24 hrs, as shown by qPCR analysis." (PMID 23597096, 2013). "The secretory patterns of tumor-primed mononuclear cells are lineage-specific: PBMC co-secrete EREG and OSM, while MΦ co-secrete HB-EGF and OSM." (PMID 23597096, 2013). "Additionally, neutrophils secrete cytokines including TGF-β, VEGF, OSM, IL-10, and HGF, which directly promote tumor angiogenesis and tumor progression." (PMID 40761249, 2025). "In particular, our analysis revealed increased expression of various immune modulatory molecules (CD274 (PD-L1), OSM, PTGES2, CD36, and MSR1) by tumor-infiltrating monocytes and neutrophils suggesting an immune suppressive role is adopted following infiltration into the TME." (PMID 39932553, 2025). "For instance, a study involving prostate cancer patients who underwent a 12-week exercise program revealed increased serum levels of oncostatin M and myokines, decreased IGF levels, and a slowdown in tumor cell growth, supporting the potential tumor-inhibitory effects of exercise." (PMID 39346906, 2024). "Moreover, CellChat analysis unveiled ligand-receptor pairs mediating communication between tumor epithelial cells and disulfidptosis-related TME subgroups, such as TNFSF12-TNFRSF12A, TNF-TNFRSF1A, OSM-(OSMR+IL6ST), OSM-(LIFR+IL6ST), HBEGF-EGFR, and EREG-EGFR." (PMID 38292868, 2024). "In addition, tumor cells also showed increased expression of OSMR, which suggests the presence of the OSM-OSMR axis in metastatic ccRCC potentially acting as an independent RANKL-inducing pathway." (PMID 38281962, 2024). "SCAMs promote LY6D- tumor epithelial proliferation via secretion of the ligand oncostatin-M (OSM), a role independent of immunosuppression." (PMID 37164949, 2023).
tumor (continued). "In addition, neutrophils synthesize and secrete oncostatin M and vascular endothelial growth factor (VEGF) to initiate angiogenesis and stimulate tumor growth, thereby furthering the invasion and metastasis of the tumor." (PMID 37064093, 2023). "In addition, neutrophils can also secrete bioactive substances that promote tumor progression, including VEGF, MMP9, Oncostatin M (OSM), IL-1β, ​​TNF-a, IL-8, CXCL3, ROS." (PMID 37644468, 2023). "Our snRNA-seq data also showed that macrophages express OSMR’s major ligand oncostatin M (OSM), suggesting that ccRCC tumor cells may interact with macrophages through OSM signaling transduction." (PMID 36973268, 2023). "Although no significant changes in OSM and OSMβR transcript levels were observed between tumor and peri‐tumoral tissue, these transcript levels were once again significantly increased, compared with the livers of mice fed the CDAA diet." (PMID 35064579, 2022). "In non-tumor cells, EGFR-OSMR can be activated synergistically by the ligands EGF and OSM." (PMID 35954323, 2022). "In contrast, injection of the same cells into Osm−/− mice results in a significantly reduced tumour burden, shown by iRFP intensity, tumour volume and tumour weight, demonstrating a systemic role for OSM in primary tumour growth." (PMID 34921158, 2021). "In our studies, suppression of tumor-produced OSM or the absence of OSM in OSM-KO mice resulted in reduced numbers of CTCs, whereas injection of recombinant OSM increased CTCs." (PMID 29898744, 2018). "In all the tumor tissues overexpressing PIM1/2, we detected a clear increment in the expression of IL-6, while NFAT2 was clearly increased and we observed an increase in two NFAT2 targets, cMYC and OSM." (PMID 28938604, 2017). "JAKs are key participants in signaling networks fueled by a variety of cytokine and growth factor receptors in the tumor microenvironment, including IL-6, IL-11, IL-27, interferon (IFN-α/β/γ) oncostatin M (OSM), leukemia inhibitory factor (LIF), epidermal growth factor (EGF) and others." (PMID 29190997, 2017). "In addition, TANs also release cytokines like Oncostatin M, which induce VEGF and then stimulate angiogenesis to support tumor metastasis." (PMID 28223716, 2017). "Taken together, these data showed that STAT1 reduced SLUG expression and mediated the OSM-dependent suppression of cell motility in vitro and tumor metastasis in vivo, while STAT3 did not interfere with this effect even though it was phosphorylated." (PMID 27486982, 2016). "In addition, TANs promoted tumor invasion by releasing of ROS, growth factors such as hepatocyte growth factor (HGF), and cytokines like oncostatin M." (PMID 27446967, 2016). "Studies found that oncostatin M and transforming growth factor 1 (TGF1) could mediate the binding of HA to CD44 in tumor cells originated from lung epithelia, leading to the glycosylation and phosphatization of CD44." (PMID 21294926, 2011). "Multiple lines of transcriptomic evidence in tumor-educated THP1 cells point to STAT3 pathway activation, including upregulation of canonical STAT3 targets (SOCS3, CISH, BCL3, JUNB, PIM1) and increased expression of STAT3-activating ligands (IL6, IL11, LIF, OSM) in response to TNBC contact." (PMID 41514627, 2025). "According to the results of the cell proliferation assay, there was no discernible difference in the proliferation of the ccRCC tumor cells between the control group and the group with high OSM expression, indicating that high OSM expression does not stimulate the proliferation of ccRCC tumor cells." (PMID 38034950, 2023). "Additionally, tumor-secreted factors, including IL-6 and OSM, activate Signal Transducer and Activator of Transcription 3 (STAT3) within M-MDSCs, which, in turn, drive a mesenchymal and invasive phenotype in the tumor cells." (PMID 34830776, 2021). "Finally, the absence of OSM (OSM-KO mice) led to a 30% reduction of tumor size and reduced M2 polarization in the tumor microenvironment." (PMID 30559930, 2018).
tumor (continued). "The expression of other STAT3-signalling cytokine, such as IL-6, could explain the absence of total tumor regression and the similar cytokine expression and immune infiltration profiles between OSM-KO mice and their WT littermates." (PMID 30559930, 2018). "Tumor cell-secreted factors trigger two stereotype secretory profiles in peripheral blood monocytes and differentiated macrophages: monocytes secrete epiregulin (EREG) and oncostatin-M (OSM), while macrophages secrete heparin-binding EGF-like growth factor (HB-EGF) and OSM." (PMID 23597096, 2013). "Moreover, no overt metastasis is observed in Osm−/− animals, but further studies are needed to establish a mechanistic link between OSM signalling and metastasis—in particular given an established relationship between primary tumour size and metastatic dissemination." (PMID 34921158, 2021).